DNMT1 (DNA methyltransferase 1)
Diseases named in the same sentence as DNMT1 in open-access papers (continued):
Sharing a sentence is not in itself a finding about the gene and the disease.
tumor (continued). "DNMT1 is the major DNMT that expressed ubiquitously and has important role in tumorigenesis by silencing tumor suppressor genes by hyper-methylation." (PMID 29137356, 2017). "In contrast, constitutively high MYC levels in tumor cells drive the expression of DNMT1 and DNMT3B." (PMID 29100357, 2017). "Consistent with this, β-elemene inhibited tumor growth, phosphorylation of Stat3, expressions of DNMT1 and EZH2 in a mouse xenograft model." (PMID 28360411, 2017). "Among the top six significant miRNAs from the combined analysis, miR-342, which targets the DNMT1 and inhibits tumor cell proliferation or invasion, has been suggested as a tumor suppressor in CRC." (PMID 27096956, 2016). "DNA demethylation induced by 5-Aza-CdR treatment and Dnmt1 knockdown significantly reduced the cell proliferation of the tumor organoids." (PMID 27143627, 2016). "We demonstrated that the expression and enzymatic activity of DNMT1 was significantly increased in tumor tissues from MEN1 patients, Men1 KO mice, and Men1 null cell lines." (PMID 26871472, 2016). "HM miR-148a-3p regulates the DNMT1 enzyme, participating in liver development, and also acts as a tumour suppressor." (PMID 27074017, 2016). "Microarray analyses of the tumor organoids after 5-Aza-CdR treatment and Dnmt1 knockdown revealed that interferon-responsive genes were activated by DNA demethylation." (PMID 27143627, 2016). "Tumor expression of DNMT1 differed by molecular subtype: it was higher in TNBC and lower in luminal A (p < 0.001) samples." (PMID 27071379, 2016). "Consistent with this, PPI inhibited tumor growth, protein expression levels of p65, DNMT1 and EZH2, and increased phosphorylation of SAPK/JNK in vivo." (PMID 27421653, 2016). "In conclusion, CagA increased tumor suppressor genes hypermethylation via stimulating DNMT1 expression through the AKT-NFκB pathway." (PMID 26848521, 2016). "Taken together, these findings demonstrated that a novel tumor suppressor DBCCR1-003 regulates the expression of DBCCR1 via binding to DNMT1 and preventing DNMT1-mediated the methylation of DBCCR1 in BC." (PMID 27777512, 2016). "Tumor expression of DNMT1 was higher in inflammatory stromal type samples compared to other subtypes." (PMID 27071379, 2016). "SGI-1027, a quinoline-based compound, has demonstrated inhibitory activity against DNMT1, DNMT3a, and DNMT3b, possibly by interacting with the DNA substrate, which results in demethylation and reactivation of tumor suppressor genes." (PMID 27651838, 2016). "Cells with low DNMT1/3B expression are prone to apoptosis, which is consistent with the result that the tumor size (AJCC T stage) was relatively smaller than in the other groups, leading to a better survival rate." (PMID 27806083, 2016). "We further verified these findings by examining the effects of silencing DNMT1 on tumor growth in nude mice." (PMID 27286455, 2016). "Several studies report that RNAi mediated depletion of DNMT1 or microRNA mediated suppression of DNMT1 restores tumor suppressor genes expression through the reversal of DNA hypermethylation." (PMID 27286455, 2016). "MiR-148a involves in DNA methylation process via targeting DNMT-1 and, more importantly, serves as a tumor suppressor in hepatocellular carcinogenesis." (PMID 27518872, 2016). "In order to demonstrate the molecular mechanisms underlying inhibitory effects of silencing DNMT1 on ESCC cells, we investigated the effect of silencing DNMT1 on expression of tumor suppressor genes." (PMID 27286455, 2016). "To investigate the effect of DNA demethylation on tumor organoids, we established intestinal tumor organoids derived from tumors of ApcMin/+ (Min) mice and subjected them to treatment with 5-Aza-CdR and knockdown of Dnmt1." (PMID 27143627, 2016).
tumor (continued). "Tumor growth of the U251/TM xenograft was inhibited by pcDNA-DNMT1 pretreatment and boosted by DNMT1-small hairpin RNA pretreatment." (PMID 26337869, 2015). "DNMT1 was well distributed in the cytoplasm and nuclei of tumor cells or glands, while DNMT3a and 3b were well distributed only in the cytoplasm, as shown by staining a dark brown color." (PMID 25823664, 2015). "Further studies confirmed that genistein inhibits DNMT1, DNMT3a and DNMT3b, and leads to activation of silenced tumour suppressor genes." (PMID 26161152, 2015). "Other studies revealed down-regulation of DNMT1 expression in tumor cells, via increased abundance of a regulatory miRNA (miR29b) or over-expression of a partner protein (UHRF1) that induces DNMT1 destabilization." (PMID 26504497, 2015). "The phase of DNMT1 depletion at the origin of CG gene activation in tumors likely occurs transiently during tumor development." (PMID 26504497, 2015). "Uhrf1, which has been reported to be over-expressed in HCC, can recruit the maintenance DNA methyltransferase Dnmt1 to repress tumor suppressor gene expression." (PMID 25549359, 2014). "In the present work, we reported that the disruption of the DNMT1/PCNA/UHRF1 complex acts as an oncogenic event of the tumor transformation of brain (astrocytes), breast, lung and mesothelial cells." (PMID 24637615, 2014). "miR-152 is gaining interest as a factor in various tumor types; a recent report concerning nickel sulfide-transformed human bronchial epithelial (16HBE) cells demonstrated that the miRNA-152/DNMT1 relationship develops early in transformed cells." (PMID 25004396, 2014). "The mean DNMT1 expression in tumor tissues was increased by 38% when compared with paired control tissue samples (p = 0.0098)." (PMID 24849932, 2014). "Distribution of 5-MeC levels in different tumor locations and correlations of 5-MeC and DNMT1 levels for UCs using immunohistochemistry (n = 150)." (PMID 25561224, 2014). "Since we observed that numerous miRNAs in our panel were influenced by methylation, and the methyltransferase DNMT1 is a regulator of DNA hypermethylation in various tumor types, we sought to explore the miR-152/DNMT1 relationship in PCas." (PMID 25004396, 2014). "Surprisingly, the mean levels of DNMT1, DNMT3a, and DNMT3b overexpression have turned out to be quite similar among different tumor types." (PMID 24822169, 2014). "shRNA-mediated knockdown of DNMT1 similarly suppressed tumor growth, consistent with previous results." (PMID 24623306, 2014). "Because DNMT1 has been characterized as one of the main enzymes responsible for maintenance of global methylation patterns in tumor-related genes, we investigated the role of DNMT1 on miR-152." (PMID 25004396, 2014). "For example, lowering the level of DNMT1 with a Dnmt1 null over Dnmt1 reduced activity genotype protects against tumor formation in Apc(Min) mice." (PMID 24236046, 2013). "Knockdown of DNMT1 and 3b expression arrests tumor cells at the G1 phase of the cell cycle and induces apoptosis." (PMID 24423239, 2013). "UHRF1 is an oncogene protein known to bind to methylated DNA and to recruit the DNMT1 to regulate tumor suppressor gene expression including p16INK4A." (PMID 23688286, 2013). "Inhibition of DNMT1 is crucial for disrupting the aberrant methylation at tumor-relevant genes and inhibition of DNMT3B is probably needed to interfere with de novo methylation." (PMID 22563479, 2012).
tumor (continued). "We treated HBEC and B2B cells with tobacco carcinogen NNK, which is known to lead to accumulation of DNMT1 and increased tumor suppressor hypermethylation in NSCLC." (PMID 22403725, 2012). "The gene expression profiling of the 63 tumours of patients with TRG2 showed, that high expression levels of GSK3B, DNMT1 and CTNNB1 were significantly associated with better survival (conditional inference test: p = 0.006, 0.041, and 0.043, respectively)." (PMID 22970250, 2012). "From the results of the microarray analysis, we selected 5 genes i.e., K-ras, c-MYC, DNMT1, Tpd52, CDKN1b for PCR confirmation because they are already considered as tumor-related genes." (PMID 22206623, 2011). "In tumor tissue as compared to normal brain, DNMT1 andDNMT3b were significantly upregulated (DNMT1: 2.5-fold, DNMT3b: 3.2-fold, p<0.001); thedegree of upregulation did not correlate with MGMT promotermethylation status and MGMT mRNA expression." (PMID 21365007, 2011). "More importantly, higher levels of DNMT1 mRNA transcripts, but lower levels of miR-185 were detected in primary glioma tissues, as compared with that in non-tumor brain tissues." (PMID 21962230, 2011). "Abnormal DNA methylation is thought to be a major early event in the development of tumours where DNA methyltransferases (DNMTs), DNMT1, DNMT3A and DNMT3B have been identified as DNA methylation functional enzymes in eukaryotic cells." (PMID 20128888, 2010). "Other studies have expanded these observations showing that DNMT1, a downstream target of Fos, is upregulated in chemoresistant tumor cells." (PMID 21108789, 2010). "The Dnmt1-immunoprecipitation indicated that it was the case because the quantity of PCNA and UHRF1 decreased when the tumor grade increased while the quantity of Dnmt1 immunoprecipitated remained unchanged." (PMID 20613874, 2010). "This evidence has been further confirmed showing that the selective silencing of DNMT1 and DNMT3b greatly reduces the chemoresistance of tumor cells overexpressing DNMTs isoenzymes." (PMID 21108789, 2010). "A significant amount of research has been carried out over the years to see if the levels of Dnmt1 control the aberrant methylation pattern in tumor cells and in cells where Dnmt1 was stably overexpressed." (PMID 19262751, 2009). "Overall, DNMT1-targeted therapies could suppress tumor growth, prevent metastasis, and help overcome the aggressive nature of TNBC." (PMID 41602389, 2026). "Here, we show that genetically deleting the epigenetic factor DNA methyltransferase 1 (Dnmt1) in endothelial cells (ECs) reduces angiogenesis while imparting profound changes to the tumor immune microenvironment (TIME), including increased proportions of CD4+ memory T cells and NK cells." (PMID 42156591, 2026). "Moreover, applying pharmacological or genetic methods to target DNMT1 in CSCs specifically decreased their self‐renewal and in vivo tumour formation capacity." (PMID 40387409, 2025). "Higher DNMT1 expression and lower DACH1 expression were associated with poorer clinical outcomes, including worse tumor differentiation, lymphatic metastasis, and advanced tumor stages." (PMID 40370966, 2025). "Moreover, the upregulation of miR‐152 has a profound inhibitory effect on tumour development in vivo, as evidenced by a reduction in DNMT1 expression and an augmentation in the expression of TSGs." (PMID 40387409, 2025). "Similarly, inhibition of DNMT1 activity has been reported to reduce BC cell proliferation in vitro and tumor growth in vivo." (PMID 40909350, 2025). "Disruption of DNMT1 interactions can lead to global DNA hypomethylation and tumor growth." (PMID 39996888, 2025). "RT‐qPCR and Western blot analyses showed that miR‐217 and TSHZ2 expressions were significantly increased in the tumor tissues of the Lv‐miR‐217 + oe‐NC group compared to the Lv‐NC + oe‐NC group, whereas DNMT1, SHH, and GLI1 expression were significantly decreased." (PMID 40909350, 2025).
tumor (continued). "Based on these results, we hypothesize that plasma DNMT1 originates from tumor tissues, although further research is needed to confirm this hypothesis." (PMID 40317882, 2025). "Epigenetic enzymes such as DNMT1 could lead to transcription repression by catalysing genomic DNA methylation and are usually aberrantly expressed in human tumours." (PMID 40387409, 2025). "Furthermore, recent studies have highlighted DNMT1 as a key enhancer of tumor progression by promoting EMT." (PMID 39980567, 2025). "Moreover, DNMT1 inhibition induces the reduction in MDSCs, leading to tumor growth in an experimental model of OSCC." (PMID 40650111, 2025). "Meanwhile, we intend to clarify whether the plasma DNMT1 could influence tumor progression and metastasis through additional methylation of the nucleic acids in peripheral blood." (PMID 40317882, 2025). "Remarkably, DNMT1 is thought to be a cause of TNBC by hypermethylating the promoters of ER, several oncosuppressors, and EMT-related target genes (including CDH1, encoding for E-cadherin), thus promoting tumor growth, autophagy, and metastasis." (PMID 40141248, 2025). "Furthermore, LINC00173 upregulation suppressed DNMT1 expression while inhibiting cell proliferation and tumour growth in HQ‐MT cells." (PMID 40387409, 2025). "Furthermore, reduced expression of HOTAIR and DNMT1 led to decreased tumour volume and weight in mice injected with CML cells." (PMID 40387409, 2025). "Further, in vivo experiments confirm that DNMT1 silencing reduces tumor growth in mouse models." (PMID 41462671, 2025). "And the expression of DNMT1 was strongly correlated with that of PCSK9 in tumor tissues." (PMID 40125618, 2025). "Similarly, miR-139-5p can target DNMT1 and inhibit osteosarcoma growth, with its overexpression reducing tumor growth in vivo." (PMID 40868849, 2025). "However, tumor differentiation, lymphatic metastasis, and tumor stage were significantly associated with DACH1 and DNMT1 expression." (PMID 40370966, 2025). "Targeting DNMT1, in particular, may disrupt survival mechanisms in BrM cells, aiding in the elimination of dormant tumor cells." (PMID 40016470, 2025). "Also, elevated global DNA methylation levels and increased expression of DNA methyltransferases (DNMT1, DNMT3A, DNMT3B) have also been linked with poor prognosis and higher tumor aggressiveness." (PMID 41150792, 2025). "miR-152-3p, another tumor-suppressive miRNA, regulates epigenetic modifiers such as DNMT1 and PTEN." (PMID 41462933, 2025). "Another experiment explored the potential role of DNMT1 in supporting tumor antigenicity." (PMID 39996888, 2025). "While DNMT1 often functions as an oncogene by maintaining aberrant methylation patterns, it may also act as a tumor suppressor in certain therapeutic contexts." (PMID 41381440, 2025). "Notably, we observed a strong association between DNMT1 levels and metastasis, suggesting that DNMT1 is more likely to be released into the peripheral blood during tumor metastasis." (PMID 40317882, 2025). "Importantly, DNMT1‐mediated changes in genomic methylation precede tumor cell phenotypic changes temporally." (PMID 40317882, 2025). "The depletion of DNMT1 leads to global cellular hypomethylation, which is hypothesized to reactivate tumor suppressor genes that have been silenced via hypermethylation, thereby leading to tumor inhibition and apoptosis." (PMID 40681875, 2025). "Furthermore, in vivo, findings indicated that the overexpression of miR‐139‐5p has a mitigating impact on tumour growth by downregulating the expression of DNMT1." (PMID 40387409, 2025). "Notably, NEAT1 silencing impeded tumour growth and decreased expression levels of Ki‐67, DNMT1 and mTOR, whereas it concurrently increased miR‐185‐5p expression in an in vivo setting." (PMID 40387409, 2025). "This cytidine analog depletes intracellular DNMT1, and it has been hypothesized that DNMT1 depletion leads to hypomethylation and de-repression of methylated tumor suppressor genes." (PMID 40681875, 2025).
tumor (continued). "Specifically, downregulation of transcription factors and subsequent decrease in miR-126 levels leads to increased expression of HOTAIR, EZH2, and DNMT1, thus impairing the epigenetic control of genes involved in differentiation, development, and tumor suppression." (PMID 40141248, 2025). "Paired pre- and on-treatment (cycle 1 week 3) tumor biopsies were collected during the expansion phase to assess changes in expression of DNMT1 and the epigenetically regulated tumor suppressor protein p16 by immunohistochemistry (IHC), as well as changes in genome-wide DNA promoter methylation." (PMID 41428220, 2025). "DNMT1 is responsible for maintaining DNA methylation patterns during cell division, and its downregulation could lead to the reactivation of tumor suppressor genes that were previously silenced by hypermethylation." (PMID 41321870, 2025). "Additionally, when DNMT1 expression was silenced, it resulted in the inhibition of tumour growth in vivo." (PMID 40387409, 2025). "This review discusses the interaction between DNMT regulators and DNMT1, its binding partners, the connection between DNA methylation and tumors, how these processes contribute to tumor development, and DNMT inhibitors’ advancements and pharmacological properties." (PMID 39996888, 2025). "Interestingly, cancer cells trigger DNMT1 activation, remolding CAFs into pro-tumor phenotypes via Socs1 gene methylation in pancreatic cancer." (PMID 39858465, 2025). "Additionally, by employing chemogenetic CRISPR-Cas9 screens, we discovered that SMO inhibition acts synergistically with DNMT1 inhibition in suppressing tumor proliferation in murine as well as PDOX (patient-derived xenografts organoids) SHH-MB models." (PMID 39107797, 2024). "This may suggest that DNMT1 and SOX9 are independently regulated under YAP1-driven HC-originated CCA tumor region, while the NRAS-SOX9-DNMT1 signaling cascade may be active in Akt-NRAS CCA tumor cells." (PMID 39273023, 2024). "At the epigenetic level, it has been demonstrated that EGCG inhibits the activity of DNMTs (particularly DNMT1) in several tumor cell lines, including breast, colon, prostate, and esophageal tumor cells, thereby promoting the reactivation of antioxidant enzymes." (PMID 39858410, 2024). "Noteworthy contributions of Kindlin-2 to BC pathogenicity include the regulation of HIF-1α-mediated activation of tumor angiogenesis, mitotic spindle assembly through inhibiting histone deacetylase 6, maintenance of α-tubulin acetylation, and stabilization of DNA methyltransferase 1 (DNMT1)." (PMID 39300257, 2024). "In case of GC exposure, GC can cause hypomethylation through downregulation in the expression of DNMT1, a process described in the AtT20 corticotroph tumor cell model, or through GC hindering DNMT activity, particularly DNMT1, as demonstrated in the retinal cell (RPE) line." (PMID 38517306, 2024). "The enzyme DNMT1 and other DNMTs function to transfer a methyl group from S-adenyl methionine (SAM) to the 5 position of cytosine to generate C5-methylcytosine (5-mC) in the context of CpG islands, and is implicated in silencing tumor suppressor genes." (PMID 39057134, 2024). "Furthermore, DNA methylation contributes to the silencing of DNMT1 expression and the acquisition of tumour stem cell features by normal liver cells." (PMID 39462685, 2024). "Moreover, the phosphorylation of the Rb protein decreased in the sh-DNMT1 group, further supporting our discovery that DNMT1-remodeled DNA hypomethylation can inhibit tumor growth by concurrently suppressing the PI3K-AKT and CDK2-Rb signaling pathways." (PMID 38755637, 2024). "In the first one, aimed to assess whether dual inhibition of G9a and DNMT1 affected tumor growth and metabolic uptake, we used immunocompromised mice, where A549 cells were subcutaneously injected." (PMID 39488528, 2024). "Moreover, tumor-bearing mice in which DNMT1 was targeted exhibited a notable stability in both blood glucose and serum insulin levels." (PMID 38755637, 2024).